HIF1A (hypoxia inducible factor 1 subunit alpha)
Diseases named in the same sentence as HIF1A in open-access papers (continued):
Sharing a sentence is not in itself a finding about the gene and the disease.
Obesity (continued). "Besides inflammation, other mechanisms can modulate the effects of obesity in cancer patients, including alterations of insulin-like growth factor pathways, induction of hypoxia and HIF-1α signaling, and modulation of microbiota." (PMID 41278286, 2025). "Furthermore, ATMs of the M1 phenotype activate the transcription factor HIF-1α; as a result, these hypoxic ATMs agglomerate to form CLSs and express elevated iNOS and IL-1β as obesity progresses." (PMID 41287647, 2025). "The activity of HIF-1α is increased in adipose tissue in obesity." (PMID 39198360, 2025). "In obesity, the expression of HIF-1α in adipose tissue is increased." (PMID 39941741, 2025). "Some obesity-relatedgenes regulated by HIF-1α also regulate energy metabolism." (PMID 40062973, 2025). "Previous reports suggest that HIF-1α may indirectly influence PGC-1α activity by suppressing sirtuin 2 (SIRT2)-mediated deacetylation in dietary obesity mouse models." (PMID 40713487, 2025). "However, in obesity, persistent HIF-1α activation leads to excessive and disorganized angiogenesis, which is insufficient to resolve hypoxia." (PMID 41287647, 2025). "In the early stages of obesity, an increase in saturated FFAs drives excessive oxygen consumption by adipocytes, resulting in localized hypoxia and the activation of hypoxia-inducible factor 1-alpha (HIF-1α)." (PMID 41226331, 2025). "Serpina3c global knockout (KO) mice, adipocyte-specific Serpina3c overexpressing mice, Serpina3c knockdown (KD) mice, and hypoxia-inducible factor 1 alpha (Hif1α) KD mice were fed a high-fat diet (HFD) for 16 weeks to generate obesity-related hypertriglyceridemia mice models." (PMID 39693610, 2025). "Based on this functional antagonism, we propose that dual-targeting inhibition of HIF-1α alongside activation of HIF-2α may synergistically ameliorate obesity-induced inflammation and IR." (PMID 41039626, 2025). "Typically, the expression of HIF-1α in macrophages may trigger adverse physiological responses by regulating macrophage metabolic reprogramming and inflammation, leading to obesity and/or IR." (PMID 41039626, 2025). "Furthermore, the inhibition of HIF-1α has the potential to ameliorate obesity phenotypes, such as increased insulin tolerance and adipogenesis." (PMID 39900792, 2025). "The mechanistic framework we present here, namely, estrogen-mediated suppression of PS via ERα and obesity-induced HIF1α stabilization, may extend beyond the studied population." (PMID 41243971, 2025). "Suppression of pathological activation of HIF1α signaling has been shown to increase the relative frequencies of adipogenic gWAT APCs and iWAT DPP4 + APCs, which is associated with enhanced protective adipocyte hyperplasia in obesity." (PMID 38509584, 2024). "Elevated levels of HIF-1α have been observed in the adipose tissue of obese mice and humans, correlating with increased adiposity and indicating the progressive worsening of hypoxia with the severity of obesity." (PMID 39337290, 2024). "However, adipose tissue‐specific inhibition of HIF1α was also demonstrated to induce obesity and inhibit BAT thermogenesis." (PMID 39348266, 2024). "Moreover, this cytokine‐induced remodeling of the microenvironment continues through the LINK‐A‐activated HB‐EGF/HIF1α loop, leading to adipose tissue dysfunction and impairments in adaptive thermogenesis, ultimately leading to obesity in mice." (PMID 38145352, 2024). "To further validate the beneficial role of intestine-specific HIF-1α overexpression on the improvement of metabolic phenotypes, we fed mice with HFr in the presence of a high-fat diet (60% Kcal fat) (HFHFr), which is known to induce obesity and MASLD." (PMID 39585307, 2024). "Additionally, NOX5 is implicated in activating HIF-1α in normoxic conditions, and obesity induces a signaling cascade in adipocytes that leads to the activation of HIF-1α." (PMID 39596205, 2024).
Obesity (continued). "In particular, recent findings revealed the significant role for HIF1α signaling in controlling gene expression associated with fibrogenesis and adipogenesis in adipose stromal cells, and thus impact the metabolic health of WAT in obesity." (PMID 38509584, 2024). "Together, these data suggest that the HIF-1α pathway, which is activated in obesity and contributes to chronic inflammation and fibrosis, may also play a role in the pathophysiology of AF." (PMID 38247541, 2024). "Increased oxygen consumption of adipocytes in obesity has been shown to enhance HIF-1α expression." (PMID 36961533, 2023). "CUX1, NANOG, GATA4 and HIF1A plays a vital role in the patients with obesity." (PMID 36837510, 2023). "HIF1α expression is associated with VEGF activation and is linked to placental formation and obesity, which may contribute to high HIF1α expression in GDM." (PMID 38234430, 2023). "A previous study indicated that HIF-1α inhibition ameliorated obesity and insulin resistance." (PMID 37108146, 2023). "In obesity, pathological AT remodeling featured by increased levels of inflammation, fibrosis and adipocyte hypertrophy is driven by a variety of key regulatory pathways including HIF1α signaling pathway." (PMID 36875847, 2023). "Hence, we generated a doxycycline-inducible adipocyte Hif1a knockout mice with features of metabolically healthy AT remodeling in the context of concurrent sarcopenia and obesity." (PMID 36875847, 2023). "However, sustained obesity resulted in reduced angiogenesis, particularly in the subcutaneous AT, along with an induction of Hif1a expression in visceral AT ECs." (PMID 36400935, 2022). "To investigate the impact of chronic constant light exposure on the development of obesity-related kidney disease, we utilized an HFD-induced obesity model, and explored effects of constant light exposure on HFD-induced renal injury and its association with HIF1α signal pathway." (PMID 35966094, 2022). "Moreover, the HFD-induced obesity activated tissue hypoxia, upregulated the expression of HIF-1α, and influenced autophagy by decreasing the p-AMPK/AMPK ratio and increasing the p-mTOR/mTOR ratio in the hippocampus." (PMID 36188454, 2022). "Moreover, HIF-1α upregulation in adipose tissue can induce obesity by suppressing BAT thermogenesis." (PMID 35967789, 2022). "Hypoxia induces adipocyte death and consequent macrophage recruitment; these infiltrating cells, regulated primarily by HIF-1α, play a crucial role in initiating obesity-related disorders, including metabolic reprogramming, insulin resistance, and inflammation." (PMID 35450048, 2022). "Oxidative stress that occurs in obesity and autoimmune diseases (AIDs) induces activation of the mTORC1 pathway, which provides glucose uptake and aerobic glycolysis by modulating the transcription factor HIF-1α." (PMID 34944566, 2021). "In addition, HIF1α is stabilized and promoted mitochondrial complex IV dysfunction (decreased activity and stability) in age-dependent obesity." (PMID 34889901, 2021). "Owing to its role in upregulating glycolytic enzymes, it seems likely that HIF1α could improve glucose handling in obesity and diabetes." (PMID 34692739, 2021). "However, there was a clear increase in AT HIF1A protein abundance in class III obesity with actual hypoventilation and an intermediate response in class III obesity without hypoventilation." (PMID 33758342, 2021). "In conclusion, this study demonstrates that losartan attenuated hepatic LDs accumulation and enhanced mitochondrial function and M2 macrophage polarization, possibly through partial effects by modulating HIF-1α signaling, and is a major link between obesity and NAFLD." (PMID 34360607, 2021). "These mice have lower arterial oxygenation suggestive of mild hypoxia and exposure to higher plasma cytokine levels, as well as HIF-1α being stabilized and promotion of mitochondrial complex IV dysfunction (decreased activity and stability) in age-dependent obesity." (PMID 34360607, 2021).
Obesity (continued). "HIF1α expression associated with VEGF activation is related both with placenta formation and obesity that may contribute to prolonged HIF1A high expression in GDM patients." (PMID 33520443, 2021). "Accordingly, transgenic mice overexpressing an adipose tissue-specific dominant negative Hif-1α mutant developed severe obesity, insulin resistance, and accumulated enlarged lipid droplets in brown adipose tissue with decreased mitochondrial biogenesis after high-fat diet." (PMID 32389123, 2020). "HIF1α is a protein expressed in response to hypoxia and is closely related to obesity." (PMID 33080438, 2020). "Thus, it was thought that HIF1-α expression in adipose tissue acts in favour of obesity by leading to excess of fatty acid and triglycerides." (PMID 32816039, 2020). "Here, we hypothesize that in obesity, metabolic dysregulation leads to both hypoxic and pseudohypoxic stimuli that activate HIF-1α in ATM, thereby sustaining systemic low-grade inflammation, a condition that fuels insulin resistance." (PMID 32221369, 2020). "While deletion of HIF-1α reduces local and systemic IL-1β levels, and causes an enrichment of M2 macrophages in the WAT, this is not sufficient to reverse the metabolic dysfunction associated with obesity." (PMID 32221369, 2020). "Hepatocyte-specific HIF-1α knockout in mice blocked these changes induced by obesity." (PMID 33013447, 2020). "Obesity and insulin resistance are observed in mice overexpressing HIF1-α." (PMID 32816039, 2020). "Nevertheless, studies regarding HIF-1α, obesity and metabolic abnormalities are relatively limited." (PMID 32752112, 2020). "HIF1α activation in adipose tissue hypoxia is a triggering factor for obesity-induced inflammation." (PMID 33257753, 2020). "Nevertheless, our study only provides a hint; the actual role of HIF-1α in obesity-AD comorbidity remains unclear." (PMID 31920651, 2019). "These outcomes suggest that TJT may prove useful in clinical management of obesity-AD comorbidity treatment, an effect that may be due to regulation of HIF-1α expression." (PMID 31920651, 2019). "Taken all together, TJT might be useful in obesity-AD comorbidity treatment because it improves clinical symptoms, and this may be due to its HIF-1α regulating effect." (PMID 31920651, 2019). "Regarding the pathological similarity between asthma and AD, the role of HIF-1α and cytokines, especially IL-5 in particular, may give an answer to the unrevealed mechanism of obesity-AD comorbidity." (PMID 31920651, 2019). "Vit.D deficiency during pregnancy stimulates the proliferation and differentiation of pre-adipocytes, which may be associated with altered methylation of genes such as Vldlr and Hif1α, leading to offspring obesity." (PMID 31426337, 2019). "However, caution should be taken since chronic systemic HIF1α inactivation (genetic or pharmacological manipulation) attenuates WAT expansion and obesity despite of the HIF1a-dependent beneficial metabolic effects in the hypothalamus." (PMID 30443205, 2018). "One might also hypothesise that during the earlier stages of HFD-induced obesity HIF-1α is important for controlling other metabolic properties of macrophages not related to cytokine production." (PMID 29333574, 2018). "Moreover, it is well established that levels of HIF-1α are elevated in the adipose tissues of obese mice, exerting important roles in the development of obesity and insulin resistance." (PMID 30619282, 2018). "Similar to obesity, HIF-1α and HIF-2α have divergent roles in colon cancer development." (PMID 30619282, 2018). "Along the role of HIF-1α in the white adipose tissue development, it might be possible that HIF1α actions favoring obesity in WAT overrides that HIF1α-dependent repression of food intake." (PMID 30443205, 2018).
Obesity (continued). "HIF1A overexpression was significantly associated with poor prognosis and higher colorectal cancer-specific mortality, whereas HIF-2α was not related with clinical outcome and exhibited an inverse association with high tumor grade and obesity." (PMID 30619282, 2018). "Other mouse models suggest that adipose HIF-1α has beneficial effects on metabolic health, e.g. by protecting against high fat diet-induced obesity, insulin resistance and glucose intolerance as well as by augmenting mitochondrial biogenesis, energy expenditure and thermogenesis." (PMID 28642579, 2017). "The exact role and compartmental localization of HIF-1α in skeletal muscle regeneration in a model of obesity remains unclear and warrants further investigation." (PMID 28725215, 2017). "It indicated that increased GPD1L which can inhibit HIF-1α activity in adipose tissue might have significant therapeutic potential in reducing obesity and insulin resistance." (PMID 28496128, 2017). "Our findings indicated that increased GPD1L which can inhibit HIF-1α activity in adipose tissue might have a significant therapeutic potential in reducing obesity and insulin resistance." (PMID 28496128, 2017). "Adipose tissue HIF1A activity is influenced by multiple signals, including adipogenesis, insulin, hypoxia, and obesity, but the induction of HIF1A by E2 can induce VEGFA and thereafter promote angiogenesis, a process that is required for adipocyte differentiation and adipose tissue growth." (PMID 29196658, 2017). "Although the mechanism of HIF-1α effects on adiposity and obesity requires further investigation, compounds that inhibit HIF-1α activity in adipose tissue might have a significant therapeutic potential in reducing obesity and insulin resistance." (PMID 28496128, 2017). "HIF3A might function as an accelerator of adipogenesis in situations of excess of energetic supply and might contribute to the etiology of secondary obesity-induced pathologies by allowing a stronger induction of HIF1α-mediated proinflammatory signaling." (PMID 27346320, 2016). "Glo-1 down regulation in obesity may be driven through hypoxia signalling by hypoxia-inducible factor-1α (HIF1α), which down-regulates Glo-1 expression." (PMID 27338619, 2016). "HIF-1α has been proposed to play a key role in the promotion and maintenance of dietary obesity." (PMID 26619907, 2015). "These persistently high levels of HIF-1α in obesity could have important repercussions on the pathways regulated by HIF-1α in VAT." (PMID 26619907, 2015). "In hypertrophic adipose tissue (a frequent characteristic of obesity), NF-κB and HIF-1α are capable of overregulating the expression of genes that encode proinflammatory cytokines, such as IL-6 and TNF-α which, in turn, have direct deleterious effects on the insulin cell signaling pathway." (PMID 25944984, 2015). "A key role for HIF-1α in the promotion and maintenance of dietary obesity has been proposed." (PMID 26619907, 2015). "Further, obesity can raise mTOR levels, which is also involved in HIF-1α translation." (PMID 25069390, 2014). "Countering these effects in obesity, n-3 PUFA have been shown to improve the hypoxic AT microenvironment by reducing adipocyte size and to decrease obesity-associated expression of HIF-1α." (PMID 25360510, 2014). "Recent reports have shown that HIF-1α is involved in obesity-related metabolic dysfunction." (PMID 23050013, 2012). "HIF-1α ASO could be a candidate for treatment of obesity, fatty liver and metabolic dysfunction in humans." (PMID 23049707, 2012). "Transgenic mice with constitutive activation of adipose HIF-1α develop mild obesity, insulin resistance and glucose intolerance, while mice with tissue-specific knockout of adipose HIF-1α are protected against diet induced obesity (DIO) and metabolic dysfunction." (PMID 23049707, 2012).
Obesity (continued). "In conclusion, although hypothalamic HIF2α/HIFβ is more physiologically relevant to metabolic regulation, both HIF2α and HIF1α hold significant therapeutic potentials and can be targeted, individually or in combination, in order to counteract obesity and related metabolic diseases." (PMID 21814490, 2011). "Furthermore, the inhibition of HIF-1α prevents or reverses obesity-induced inflammation and IR." (PMID 40143173, 2025). "HIF1α activation disrupts the balance between glycolysis and fatty acid oxidation, promoting a “compensation-inhibitory model” wherein depleted core metabolic functions are compensated by other genes while non-essential pathways are suppressed, thereby exacerbating obesity." (PMID 41340654, 2025). "Moreover, HIF-1α activation can alter metabolic pathways, promoting glycolysis and angiogenesis, which support tumor growth and survival in the hypoxic tumor microenvironment, leading to the progression of gastrointestinal cancers in individuals with obesity." (PMID 40722646, 2025). "Additionally, obesity-induced tissue hypoxia fosters tumor growth through HIF-1α-mediated pathways." (PMID 40722646, 2025). "Many chemokines are downstream transcriptional targets of HIF-1α that increase the recruitment of additional immune cells into adipose tissue; in particular, M1 macrophages that play a key role in metabolic dysfunction in obesity, including insulin resistance and glucose intolerance." (PMID 39595185, 2024). "Furthermore, in white VAT and SAT, sulpiride decreased adipocyte expansion due to hypertrophy, and in the VAT prevented the expression loss of Prlr and insulin sensitivity markers Insr and Glut4, and decreased Hif1α (hypoxia marker) expression in obesity conditions." (PMID 38635745, 2024). "Therefore, we wondered whether HIF-1α is also overexpressed in the skin and serum of patients with HS and whether HIF-1α may link obesity and smoking to Th17 cell-driven dysregulations of immunity and infundibular keratinocyte hyperproliferation." (PMID 36961533, 2023). "Furthermore, a recent study identified interleukin-1 receptor-associated kinase M as the mechanism underlying HIF-1α-induced adipose tissue dysfunction in obesity, supporting the notion that HIF-1α in myeloid cells is crucial to obesity-related pathological growth of adipose tissue and systemic IR." (PMID 37153549, 2023). "Therefore, HIF1A and ARNT may be reasonable targets in terms of preventative interventions in individuals with a genetic predisposition towards obesity." (PMID 37899888, 2023). "However, the role of HIF1α in obesity-related kidney disease remains largely unexplored." (PMID 35966094, 2022). "Collectively, our data identify enhanced glycolysis and HIF-1α activation in ATM as key mechanisms underlying macrophage persistence in the WAT and the local and systemic expression of IL-1β, placing these immunometabolic signals at the interface of macrophage activation in obesity." (PMID 32221369, 2020). "Furthermore, mice with myeloid HIF-1α deficiency showed lower levels of IL-1β expression in both WAT and the circulation than WT mice, consistent with HIF-1α being a key mechanism underlying IL-1β expression in the setting of obesity." (PMID 32221369, 2020). "At the same time, the capillary rarefaction and the higher levels of the HIF1A we found in the SAT of the obese patients confirm the hypothesis that hypoxia could play a central role in AT dysfunction in obesity, as previously reported." (PMID 31383894, 2019). "Some suggestive studies may support the idea that HIF-1α links obesity and AD." (PMID 31920651, 2019). "In a mouse model, however, maternal placental HIF-1α protein was elevated by maternal obesity, supporting the hypothesis that obesity during pregnancy is associated with placental hypoxia, resulting in an induction of angiogenesis to enhance fetoplacental vascular growth." (PMID 31110514, 2019).